RNU6-183P (RNA, U6 small nuclear 183, pseudogene)
Gene: Small nuclear RNA gene on chromosome 5 (78,314,916 to 78,315,025, reverse strand). Ensembl gene ENSG00000200331.
Homologues: Orthologues: chimpanzee U6 (99% identical), macaque U6 (97% identical). Paralogues in human: RNU6-797P (88% identical), RNU6-1209P (86% identical), RNU6-1316P (86% identical), RNU6-196P (86% identical), RNU6-1145P (85% identical), RNU6-20P (85% identical), RNU6-35P (85% identical), RNU6-393P (85% identical), RNU6-454P (85% identical), RNU6-812P (85% identical), RNU6-115P (85% identical), RNU6-11P (85% identical), and 1285 more.